SIRT6 (sirtuin 6)
Diseases named in the same sentence as SIRT6 in open-access papers (continued):
Sharing a sentence is not in itself a finding about the gene and the disease.
tumor (continued). "In support of our findings that QM-PDAC tumours have a Warburg phenotype, we found elevated levels of HIF1A and concomitantly lower levels of its corepressor, SIRT6." (PMID 30018740, 2018). "In proliferating tumor cells, AKT not only phosphorylates FOXO3a to retain it in the cytoplasm, but also phosphorylates SirT6 at serine 338 to maintain its substrate-binding ability." (PMID 30518851, 2018). "Their results showed that SIRT6 was upregulated in a subset of HCC tissues and SIRT6 knockdown by shRNA suppressed the growth of HCC cells, induced apoptosis, and inhibited tumor growth of HCC cells in vivo." (PMID 29100306, 2017). "Overexpression of SIRT6 attenuated HepG2 and HCCLM3 cells proliferation, colony formation in vitro and tumor formation in nude mice, and resulted in the G1 phase cell cycle arrest." (PMID 29100306, 2017). "SIRT6 mRNA levels were also measured by RT-PCR in 115 HCC and 48 non-tumor specimens from HCC patients." (PMID 27824900, 2016). "SIRT6 expression was significantly higher in HCC cell lines and HCC tissues from 138 patients than in an immortalized hepatocyte cell line, THLE-2 and non-tumor tissues, respectively." (PMID 27824900, 2016). "In the present study, we found that SIRT6 is upregulated in NSCLC cell lines and patient-derived tumor tissues." (PMID 27777384, 2016). "In addition to inhibiting aerobic glycolysis, SIRT6 has been shown to promote genomic stability through facilitating DNA repair, attenuate inflammation through damping NF-κB-dependent gene expression, and function like a tumor suppressor through repressing Warburg effect in cancer cells." (PMID 25816777, 2015). "Recently, the sirtuin SIRT6 has been shown to inhibit the transcriptional output of both HIF1 and MYC, and to function as a tumor suppressor." (PMID 25085992, 2014). "Therefore, we will perform similar studies with humanized mice or immunocompromised mice injected with homogeneous tumor cells to confirm the destructive effects of UBCS039 and Sirt6 activity on immune surveillance." (PMID 41530841, 2026). "Sirt6 can increase ADO, PD-L1 and PD-1 levels; decrease IFN-γ levels; and promote M2 polarization through the upregulation of Lao1 expression, which increases tumor growth by suppressing immune surveillance." (PMID 41530841, 2026). "Increased Sirt6 expression and activity induced by UBCS039 can accelerate tumor growth by promoting macrophage polarization to the M2 type or TAMs through the upregulation of Lao1 expression, which can suppress immune surveillance of tumor cells." (PMID 41530841, 2026). "Additionally, immunohistochemical analysis of patient tissue samples revealed more positive staining for SIRT6 in normal tissue sections, while TFAM exhibited more intense staining in tumor tissues, consistent with the quantitative analysis." (PMID 41362737, 2026). "In SIRT6 TG mice, decreased TNFR2 inhibited tumour‐secreted‐TNFα induced adipose lipolysis." (PMID 39971710, 2025). "SIRT6 promotes tumorigenesis by activating oncogenic pathways such as Notch signaling, while also inhibiting necroptosis-mediated immune responses through repression of RIPK3, thereby enabling tumor immune evasion." (PMID 41463311, 2025). "Conversely, in lung cancer, prostate cancer, melanoma, and non-melanoma skin cancers, SIRT6 levels are increased, which promotes tumor progression." (PMID 41304967, 2025). "These seemingly contradictory findings suggest a context-dependent duality, whereby SIRT6 may either promote or suppress PDAC progression depending on molecular background and tumor subtype." (PMID 41463311, 2025). "Tumour weights were similar between WT + LLC and TG + LLC mice, suggesting that the SIRT6 does not affect tumour growth in mice." (PMID 39971710, 2025). "Additionally, high levels of SIRT6 attenuate ERK/p90RSK signalling and enhance Chk1‐mediated DNA repair, thus regulating the DNA damage response in tumour cells." (PMID 39778006, 2025).
tumor (continued). "In addition, SIRT6-driven metabolic reprogramming is confirmed by 18F-FDG PET/CT in xenografts, which highlights its relevance to tumor energy dynamics." (PMID 41463311, 2025). "SIRT6 overexpression decreases NOTCH3 (Neurogenic locus notch homolog protein 3) levels in U87 cells, suggesting that SIRT6 may inhibit NOTCH3 expression, reducing its tumor-promoting effects." (PMID 40710366, 2025). "This establishes SIRT6 as a tumor-intrinsic inducer of immune tolerance, not limited to a single cancer, but conserved across ovarian, cervical, hepatocellular, breast, and colorectal tumor settings." (PMID 41425553, 2025). "Moreover, SIRT6-mediated deacetylation of ELF5 stabilizes this transcription factor and modulates CCND1, suggesting an additional tumor-promoting axis." (PMID 41463311, 2025). "Mechanistically, SIRT6 modulates key signaling pathways, particularly the Wnt/β-catenin pathway, which is frequently altered in cancers and plays a central role in driving EMT and tumor metastasis." (PMID 39796040, 2024). "Additionally, a pan-cancer analysis demonstrated dysregulated expression patterns of SIRT6, LRP1, and FASN across multiple tumor types." (PMID 39071712, 2024). "SIRT6 and SIRT7, through their roles in angiogenesis, EMT, and metastasis, represent additional targets, with modulators of SIRT6, such as JYQ-42, showing potential to reduce tumor invasiveness." (PMID 39682281, 2024). "Importantly, loss of SIRT6 expression may lead to tumor formation even without the activation of known oncogenes and transformed SIRT6-deficient cells exhibit increased cancer growth and glycolysis, suggesting that SIRT6 plays an important role in both the establishment and maintenance of tumors." (PMID 38203666, 2023). "Our results based on the clinical-pathological characteristics of patients with ccRCC showed that the expression of SIRT2, SIRT3, SIRT6, and SIRT7 was increased in tumor-stage 1-4 subgroups, SIRT1 was increased in tumor-stage 1, and the expression of SIRT4 and SIRT5was decreased." (PMID 37096064, 2023). "Here, we demonstrate that lack of SIRT6 increases the number and activity of ISCs, which translates into an enhanced tumor initiating potential." (PMID 35314684, 2022). "Additionally, METTL14-mediated m6A modification maintains sirtuin 6 (SIRT6) stability by regulating the expression of ubiquitin-specific peptidase 48 (USP48) and promoting the tumor suppressive function of glycolysis to regulate the metabolic activity of HCC." (PMID 36120301, 2022). "Low levels of SIRT6 increase acetylated FOXO3, thereby inhibiting tumor development." (PMID 35463332, 2022). "For the same reasons, in our study, we do not compare effects of SIRT6 over‐expression in tumour environment with those in the non‐tumour conditions." (PMID 34212132, 2021). "Based on these data, one could argue that reduced ATP availability in the mammary gland may hinder tumor development starting from its very early stages, thus justifying the marked extension in tumor latency observed in MMTV-PyMT+/−; Sirt6+/− mice." (PMID 33482921, 2021). "In non‐tumour mice, SIRT6 over‐expression did not influence Wnt4 mRNA expression; however, in tumour‐bearing mice, gastrocnemius muscles of Tu‐Sk.T6Tg mice showed a significant downregulation of Wnt4 mRNA levels, compared with that in Tu‐CN mice." (PMID 34212132, 2021). "UQCRC2 expression was reduced by SIRT6 silencing in MDA-MB-231, but not in Sirt6+/− mouse tumor masses." (PMID 33482921, 2021). "The tumor-bearing nude mouse experiments substantiated that HCT116 cell-derived EVs transferred miR-25 to facilitate tumor formation and metastasis by inhibiting SIRT6." (PMID 33510943, 2021).
tumor (continued). "In non‐tumour condition, SIRT6 over‐expression did not alter fibre size range distribution unlike in tumour environment." (PMID 34212132, 2021). "A non-significant trend towards an increase in the number of apoptotic tumor cells per field was observed as a result of Sirt6 heterozygous deletion [5.7 ± 1 and 7.3 ± 1 in MMTV-PyMT+/−; Sirt6+/+ (n = 6) and in MMTV-PyMT+/−; Sirt6+/− (n = 4) mice, respectively; P = 0.13]." (PMID 33482921, 2021). "We found that TNF‐α was significantly downregulated by SIRT6 over‐expression in tumour environment, unlike in non‐tumour background." (PMID 34212132, 2021). "Also by using SIRT6, enzymes with a role in antioxidant defense with a potential role in tumor growth inhibition in a low concentration, they showed that RESV had an opposite result, increasing the SIRT6 levels in a concentration-dependent manner." (PMID 34805304, 2021). "Though the administration of 4HR would inhibit the growth of tumor, elevated SIRT3 and SIRT6 could play a protective role for cancer cells that survived after 4HR treatment, and these cancer cells might be more resistant to other cytotoxic cancer therapy." (PMID 34719767, 2021). "In a xenograft mouse model using HN31, which does not express Sirt6, intratumoral injection of Ad-Sirt6 significantly decreased tumor growth, volume, and weight." (PMID 33727672, 2021). "In non‐tumour condition, none of the cytokines showed any statistically significant change with SIRT6 over‐expression." (PMID 34212132, 2021). "To address this possibility, we silenced SIRT6 by RNA interference in the BC cell line MDA-MB-231, injected these cells (or cells harboring a control shRNA) subcutaneously into both flanks of nude mice, and monitored tumor growth." (PMID 33482921, 2021). "On the contrary, we observed no mortality for tumour‐bearing SIRT6 over‐expressing (Tu‐Sk.T6Tg) mice in these 2 weeks period, at which time these mice were sacrificed for further analyses." (PMID 34212132, 2021). "Overexpression of SIRT6 induced apoptosis in HCC cells and could also reduce tumor formation and tumor growth of HCC cells in in vitro and in vivo experiments." (PMID 33335996, 2020). "In addition, NAC (low concentration) and CQ, previously considered to be tumor inhibitors, were shown to promote tumorigenesis in PTC with high SIRT6 expression by inducing the Warburg effect." (PMID 32983963, 2020). "The SIRT6–PTEN interaction was found to promote apoptosis and inhibit cell proliferation in vitro through inhibition of PI3K signalling, altogether revealing a novel SIRT6/PTEN/PI3K signalling axis with tumour suppressive capacity." (PMID 33659963, 2020). "SIRT6, an H3K9 deacetylase, inhibits transcriptional activation of HIF-1α in non-tumor cells and reduces the level of glucose metabolism, but SIRT6 knockdown increased glucose uptake in mice, inhibited mitochondrial respiration, and effectively responded to nutrient deprivation." (PMID 33109235, 2020). "In prostate cancer, SIRT6 can induce EMT and enhance tumor invasion." (PMID 30675128, 2019). "A series of studies have revealed that SIRT6 functions as a tumor suppress gene, but there are still no small-molecule activators specific to SIRT6 that have been found to date." (PMID 34691990, 2019). "Combined with our previous study, we could safely draw the conclusion that upregulated SIRT6 in PTC inducing epithelial–mesenchymal transition by positive regulation of HIF-1α, thus promotes tumor progression." (PMID 30675128, 2019). "SIRT6 overexpression not only strengthens the phosphorylation of extracellular signal-regulated kinase 1/2 (p-ERK1/2) but also activates MMP9 and promotes the migration and invasion of tumor cells." (PMID 31817470, 2019). "Furthermore, IHC analysis showed that NQO1 knock-out was related with reduced level of SIRT6, XIAP and increased level of cleaved PARP in tumor tissues." (PMID 31842909, 2019).
tumor (continued). "Pharmacological activation of SIRT6 by UBCS039 was obtained in several cell lines regardless of tumor histotype and without affecting SIRT6 protein expression levels (Supplementary 1A, B)." (PMID 30250025, 2018). "SIRT6 and COX-2 are oncogenes target that promote the expression of proinflammatory and pro-survival proteins through a signaling pathway, which leads to increased survival and proliferation of tumor cells." (PMID 29556059, 2018). "Tumor volumes at endpoint for negative control and SIRT6-depleted tumors were 426.7 ± 60.9 mm3, 214.7 ± 33.3 mm3 and 240.5 ± 42.6 mm3, respectively." (PMID 27824900, 2016). "SIRT6 expression level is inversely correlated with miR‐34a in normal keratinocytes and keratinocyte‐derived tumours." (PMID 26508273, 2016). "SIRT6 knockdown by shRNA suppressed the growth of HCC cells and inhibited HCC tumor growth in vivo." (PMID 27824900, 2016). "This evidence would suggest that sirtuins also have the potential to act as tumour suppressors, and it has been hypothesised that both SIRT2 and SIRT6 act in such a manner." (PMID 26121130, 2015). "Moreover, overexpression of SIRT6 in non-small cell lung cancer (NSCLC) cells radiosensitizes them which inhibits their proliferation, further supporting the idea of SIRT6 being a tumor suppressor." (PMID 25907989, 2015). "Thus, in this cellular context, SIRT6, by regulating HIF1 and/or MYC, qualifies as a tumor suppressor." (PMID 25085992, 2014). "This interplay between SIRT7 and MYC might suggest that SIRT7 functions as a tumor suppressor by inhibiting MYC activity, similar to SIRT6." (PMID 25085992, 2014). "Pharmacological modulation of SIRT6 has shown therapeutic promise, with activators such as MDL-800 inhibiting proliferation and enhancing EGFR-TKI efficacy, while natural compounds like α-hederin exert anti-tumor effects through SIRT6-dependent glycolytic inhibition." (PMID 41463311, 2025). "Moreover, we measured the TNFR2 levels in muscle tissues of SIRT6 TG mice and WT mice, with or without tumour." (PMID 39971710, 2025). "Moreover, a pharmacological activator of SIRT6, MDL800, could completely reverse tumour‐induced lipolysis." (PMID 39971710, 2025). "However, LLC tumours were not affected by SIRT6 overexpression, and TNFR2 levels were not altered in tumour cells." (PMID 39971710, 2025). "SIRT6 binds and deacetylates nuclear PKM2 at K433, leading to the expulsion of PKM2 from the nucleus, thus eliminating its role as a nuclear protein kinase and a transcriptional coactivator, and resulting in decreased tumour cell proliferation, migration and invasion." (PMID 39778006, 2025). "Combined with SIRT expression (mRNA and protein) and the prognostic value of SIRTs (mentioned previously herein), we speculate that SIRT4 and SIRT5 might be possible tumor suppressor markers, whereas SIRT6 and SIRT7 could play an important role in promoting tumor development." (PMID 37096064, 2023). "Therefore, SIRT4 and SIRT5 potentially inhibit the occurrence and development of ccRCC, whereas high expression of SIRT3, SIRT6, and SIRT7 might have an important tumor-promoting role." (PMID 37096064, 2023). "Moreover, SIRT6 R65A mutant and G60A mutant were utilized to identify whether the defatty-acylation and ADP-ribosylation of SIRT6 also contributed to tumor progression." (PMID 33995674, 2021). "Similarly, plasma levels of WNT4 did not change significantly with SIRT6 over‐expression in the non‐tumour environment and were barely detectable." (PMID 34212132, 2021). "In contrast to targeting TGFβ, the therapeutic strategy of upregulating KLF10/SIRT6 signaling in PDAC may reduce distant metastasis without enhancing tumor proliferation." (PMID 34702956, 2021). "The inactivation of SIRT6 in cancer cells leads to the accumulation of nuclear ACLY protein and increases nuclear acetyl-CoA pools, which in turn drive locus-specific histone acetylation and the expression of cancer cell adhesion and migration genes that promote tumor invasiveness." (PMID 34573442, 2021).
tumor (continued). "In non‐tumour‐bearing mice (N.Tu‐CN and N.Tu‐Sk.T6Tg), however, no change in Cxcl10 transcript levels were observed reiterating SIRT6's context‐specificity." (PMID 34212132, 2021). "In mouse embryonic fibroblasts (MEFs), Sirt6 knockout led to tumorigenesis independent of the activation of oncogenes, suggesting that this molecule may function as a tumor suppressor." (PMID 32711549, 2020). "Considering the negative effect of SIRT6 on cellular senescence implies that it may also have the potential to promote tumor development." (PMID 31591350, 2019). "After SIRT6 induced mitochondrial dysfunction in CRC cells, the mitochondria are no longer able to properly supply energy to meet the tumor's needs." (PMID 41362737, 2026). "GLUT4 protein expression in gastrocnemius muscle of N.Tu‐CN and N.Tu‐Sk.T6Tg mice did not change significantly; however, in tumour‐bearing mice, GLUT4 was significantly upregulated with SIRT6 over‐expression." (PMID 34212132, 2021). "In our non‐tumour animals, we did not detect any significant change in the plasma FFA levels between N.Tu‐CN and N.Tu‐Sk.T6Tg mice, consistent with a previous report where FFA levels were analysed in another mouse model of SIRT6 over‐expression." (PMID 34212132, 2021).